OSBPL10 (oxysterol binding protein like 10)
Description:
Lipid transporter involved in lipid countertransport between the endoplasmic reticulum and the plasma membrane. Its ability to bind phosphatidylserine, suggests that it specifically exchanges phosphatidylserine with phosphatidylinositol 4-phosphate (PI4P), delivering phosphatidylserine to the plasma membrane in exchange for PI4P (Probable). Plays a role in negative regulation of lipid biosynthesis. Interacts with OSBPL9 to function as lipid transfer proteins. Together they form a heterodimer that localizes at the ER-trans-Golgi membrane contact sites, and exchanges phosphatidylserine (1,2-diacyl-sn-glycero-3-phospho-L-serine, PS) for phosphatidylinositol-4-phosphate (1,2-diacyl-sn-glycero-3-phospho-(1D-myo-inositol 4-phosphate), PI(4)P) between the two organelles, a step that is critical for sphingomyelin synthesis in the Golgi complex. Negatively regulates APOB secretion from hepatocytes. Binds cholesterol and acidic phospholipids. Also binds 25-hydroxycholesterol. Binds phosphatidylserine.
Synonyms: ORP10; OSBP9
Tractability: PROTAC: ubiquitination databases record sites on it; its protein half-life has been measured.
Gene: Protein-coding gene on chromosome 3 (31,657,888 to 32,077,580, reverse strand). Ensembl gene ENSG00000144645.
Subcellular location: Cytoplasm, cytoskeleton; Late endosome membrane; Golgi apparatus, trans-Golgi network membrane; Endoplasmic reticulum-Golgi intermediate compartment membrane
Subcellular location (Human Protein Atlas): Golgi apparatus; Plasma membrane; Nucleoplasm
Pathways (Reactome):
Metabolism: Acyl chain remodelling of PS
Gene Ontology:
Molecular function: cholesterol binding; phosphatidylserine binding; phosphatidylserine-phosphatidylinositol-4-phosphate exchange activity; protein binding; phospholipid transfer activity; lipid binding; lipid transfer activity
Biological process: lysosomal membrane organization; phospholipid homeostasis; phospholipid transfer to membrane; phosphatidylserine acyl-chain remodeling; intermembrane lipid transfer
Cellular component: endoplasmic reticulum-endosome membrane contact site; endoplasmic reticulum-trans-Golgi network membrane contact site; lysosomal membrane; trans-Golgi network; cytosol; membrane; cytoskeleton; endoplasmic reticulum-Golgi intermediate compartment membrane; Golgi apparatus; late endosome membrane
Genetic constraint (gnomAD): Loss-of-function variants: 49 observed, 82.37 expected, observed/expected ratio (o/e) 0.59, 90% interval 0.47 to 0.75. The upper end of that interval is the gene's LOEUF score, 0.75, which puts it in group 3 of 6, group 1 being the genes least tolerant of losing a copy. Missense variants: 920 observed, 982.24 expected, observed/expected ratio (o/e) 0.94, 90% interval 0.89 to 0.99. Synonymous variants: 418 observed, 374.03 expected, observed/expected ratio (o/e) 1.12, 90% interval 1.03 to 1.21.
Homologues: Orthologues: chimpanzee OSBPL10 (99% identical), macaque OSBPL10 (97% identical), dog OSBPL10 (95% identical), pig OSBPL10 (93% identical), rabbit OSBPL10 (92% identical), mouse Osbpl10 (91% identical), rat Osbpl10 (91% identical), guinea pig OSBPL10 (82% identical), tropical clawed frog osbpl10 (70% identical), zebrafish osbpl10b (60% identical), Drosophila melanogaster CG3860 (13% identical), Caenorhabditis elegans obr-2 (10% identical). Paralogues in human: OSBPL11 (54% identical), OSBPL9 (35% identical), OSBPL8 (25% identical), OSBPL5 (23% identical), OSBPL6 (21% identical), OSBPL7 (20% identical), OSBPL1A (20% identical), OSBPL3 (20% identical), OSBP (19% identical), OSBP2 (18% identical), OSBPL2 (13% identical).
Diseases named in the same sentence as OSBPL10 in open-access papers:
OSBPL10 is named in the same sentence as 21 diseases in open-access papers, as found by Europe PMC text mining. Sharing a sentence is not in itself a finding about the gene and the disease. The quoted sentences say what the papers report.
dyslipidemia (3 papers, 2014 to 2025). "For example, given that genetic variants in OSBPL10 affect serum lipid profiles, patients who fail to downregulate OSBPL10 postoperatively may be predisposed to persistent dyslipidemia or delayed hepatic lipid clearance." (PMID 40822952, 2025). "The identification of these protein hubs may reflect underlying pathways involved in dyslipidemia (OSBPL10), beige fat biogenesis (CUL2), fatty liver disease and insulin resistance (PRTN3)." (PMID 40822952, 2025). "OSBPL10 binds sterols and has been implicated in dyslipidemia." (PMID 40822952, 2025). "Our results show that OSBPL10--a disease susceptibility gene for dyslipidemia--may also influence systolic blood pressure (SBP)." (PMID 25519364, 2014). "OSBPL10 variation may enhance triglyceride levels in patients with dyslipidemia, which indicates that it regulates cellular lipid metabolism." (PMID 34943774, 2021).
dengue haemorrhagic fever (2 papers, 2017 to 2020). "OSBPL10 gene confers African-ancestry protection against dengue haemorrhagic fever in admixed Cubans46." (PMID 33173134, 2020).
Obesity (2 papers, 2025). Accumulation of substantial excess body fat. "Integrated protein-metabolite network analysis identified OSBPL10, CUL2, and PRTN3 as potential regulators of lipid metabolism and insulin resistance, offering insights into obesity-associated metabolic dysfunction." (PMID 40822952, 2025).
prostate carcinoma (2 papers, 2015 to 2019). A carcinoma that arises from epithelial cells of the prostate gland. "Our data confirmed that the treatment of prostate cancer cells with ENZA enhances the effect of radiation through down-regulation of NKX3-1, ZMIZ1, SPDEF and PDE9A genes and up-regulation of LAT, PTPRN2 and OSBPL10 genes in LNCaP cells, as well as up-regulation of CYP1B1 genes in C4-2 cells." (PMID 31221986, 2019).
breast carcinoma (1 paper, 2018). "In one breast cancer study, OSBPL10 mutations, which have a prevalence of 5.2%, have been suggested as potential drivers of mutations; however, the clinical impacts of OSBPL10 mutations were not described." (PMID 29731965, 2018).
cervical cancer (1 paper, 2020). A primary or metastatic malignant neoplasm involving the cervix. "A new circRNA derived from oxysterol binding protein like 10 (OSBPL10) (circOSBPL10) has not been researched in cervical cancer (CC) yet." (PMID 32831649, 2020).
dengue (1 paper, 2017). "Our functional assay clearly shows that knockdown of OSBPL10 expression reduces significantly DENV replication, a direct proof that the lower OSBPL10 expression profile in Africans protects this ancestry against dengue disease." (PMID 28241052, 2017). "Knockdown of OSBPL10 expression in THP-1 cells by two shRNAs followed by DENV2 infection tests led to a significant reduction in DENV replication, being a direct functional proof that the lower OSBPL10 expression profile in Africans protects this ancestry against dengue disease." (PMID 28241052, 2017). "The genomic and functional confirmation of the protection conferred by OSBPL10, RXRA and related lipid metabolism against dengue illness supported in this study points out potential therapeutic applications." (PMID 28241052, 2017).
ductal carcinomas (1 paper, 2007). "Majority of genes encoding proteins with enzyme activity or implicated in metabolism were also upregulated in ductal carcinomas (STK4, SLC1A2, B3GALT3, OSBPL10, CRBN, CHML, YWHAB)." (PMID 17389037, 2007).
high blood pressure (1 paper, 2014). "Variant 3_31590155 is located in a highly conserved intron (phastCons 44-way score = 294) of OSBPL10--a lipid receptor and potential candidate gene for high blood pressure." (PMID 25519364, 2014).
Hyperglycemia (1 paper, 2025). An increased concentration of glucose in the blood. "SNPs in ORP7, OSBPL11, and OSBPL10 have been linked to LDL-C levels, hyperglycemia, and cardiovascular risk factors." (PMID 40716750, 2025).
pancreatic carcinoma (1 paper, 2021). "As for OSBPL10, there were 3.438- and 3.527-fold overexpression levels in pancreatic carcinoma and 4.158- and 4.814- fold overexpression levels in PDAC, respectively." (PMID 34829830, 2021). "The data demonstrated that OSBPL3, OSBPL8, OSBPL10, and OSBPL11 were overexpressed in pancreatic cancer tissues." (PMID 34829830, 2021).
viral hemorrhagic fever (1 paper, 2019). A viral infectious disease caused by RNA viruses in the Arenaviridae, Bunyaviridae, Filoviridae, or Flaviviridae family, and characterized by a severe multisystem syndrome, with damage to the vascular system and hemorrhaging. "More specifically, the lower OSBPL10 expression profile in Africans is protective against viral hemorrhagic fever and dengue shock syndrome." (PMID 31487279, 2019).
tumor (1 paper, 2023). "The results displayed that the expressions of OSBPL3, OSBPL5, SOBPL7, and OSBPL10 were significantly correlated with tumor purity, B cell, CD8 + T cells, CD4 + T cells, macrophages, neutrophils, and dendritic cells infiltration levels." (PMID 36918840, 2023). "As to the protein expression, OSBPL2 and OSBPL3 were significantly elevated and OSBPL5, OSBPL6, OSBPL9, OSBPL10, OSBPL11 were downregulated in tumor samples." (PMID 36918840, 2023). "The results demonstrated that the protein expressions of OSBPL2 and OSBPL3 were elevated while OSBPL5, OSBPL6, OSBPL9, OSBPL10, and OSBPL11 were lowly expressed in tumor samples." (PMID 36918840, 2023).
OSBPL10 also shares sentences with these, for which no sentence is quoted: cancer (3 papers); CNS lymphomas (2); diffuse large B-cell lymphoma (1); fatty liver disease (1); infection (1); Insulin resistance (1); pancreatic ductal adenocarcinoma (1); prostate tumors (1).